CXCL10 (C-X-C motif chemokine ligand 10)
Description:
Pro-inflammatory cytokine that is involved in a wide variety of processes such as chemotaxis, differentiation, and activation of peripheral immune cells, regulation of cell growth, apoptosis and modulation of angiostatic effects. Plays thereby an important role during viral infections by stimulating the activation and migration of immune cells to the infected sites (By similarity). Mechanistically, binding of CXCL10 to the CXCR3 receptor activates G protein-mediated signaling and results in downstream activation of phospholipase C-dependent pathway, an increase in intracellular calcium production and actin reorganization. In turn, recruitment of activated Th1 lymphocytes occurs at sites of inflammation. Activation of the CXCL10/CXCR3 axis also plays an important role in neurons in response to brain injury for activating microglia, the resident macrophage population of the central nervous system, and directing them to the lesion site. This recruitment is an essential element for neuronal reorganization (By similarity).
Synonyms: IP-10; INP10; SCYB10; IFI10; crg-2; mob-1; C7; gIP-10
Tractability: Small molecule: a structure with a bound ligand is known; a high-quality ligand is known; it has a high-quality binding pocket. Antibody: a drug acting on it is in phase 2 or 3 trials; UniProt places it where antibodies can reach, with high confidence; its Gene Ontology location is reachable by antibodies, with high confidence; UniProt predicts a signal peptide or a membrane-spanning region.
Target class: Secreted protein
Gene: Protein-coding gene on chromosome 4 (76,021,118 to 76,023,497, reverse strand). Ensembl gene ENSG00000169245.
Subcellular location: Secreted
Pathways (Reactome):
Signal Transduction: Chemokine receptors bind chemokines; G alpha (i) signalling events
Immune System: Interleukin-10 signaling
Gene Ontology:
Molecular function: chemoattractant activity; chemokine activity; CXCR3 chemokine receptor binding; heparin binding; protein binding; cAMP-dependent protein kinase regulator activity; CXCR chemokine receptor binding
Biological process: adenylate cyclase-activating G protein-coupled receptor signaling pathway; antiviral innate immune response; cellular response to lipopolysaccharide; cellular response to virus; chemokine-mediated signaling pathway; chemotaxis; endothelial cell activation; G protein-coupled receptor signaling pathway; negative regulation of angiogenesis; positive regulation of monocyte chemotaxis; positive regulation of release of sequestered calcium ion into cytosol; positive regulation of T cell migration; regulation of apoptotic process; regulation of cell population proliferation; regulation of endothelial tube morphogenesis; regulation of T cell chemotaxis; T cell chemotaxis; blood circulation; cell surface receptor signaling pathway; cell-cell signaling; inflammatory response; muscle organ development; neutrophil chemotaxis; positive regulation of cell population proliferation; positive regulation of transcription by RNA polymerase II; and 11 more
Cellular component: extracellular region; external side of plasma membrane
Genetic constraint (gnomAD): Loss-of-function variants: 6 observed, 11.87 expected, observed/expected ratio (o/e) 0.51, 90% interval 0.28 to 1. The upper end of that interval is the gene's LOEUF score, 1, which puts it in group 4 of 6, group 1 being the genes least tolerant of losing a copy. Missense variants: 114 observed, 119.59 expected, observed/expected ratio (o/e) 0.95, 90% interval 0.82 to 1.11. Synonymous variants: 35 observed, 37.31 expected, observed/expected ratio (o/e) 0.94, 90% interval 0.71 to 1.24.
Homologues: Orthologues: chimpanzee CXCL10 (98% identical), macaque CXCL10 (95% identical), pig CXCL10 (85% identical), rabbit CXCL10 (83% identical), guinea pig CXCL10 (79% identical), dog CXCL10 (78% identical), mouse Cxcl10 (68% identical), rat Cxcl10 (68% identical). Paralogues in human: CXCL9 (38% identical), CXCL11 (29% identical), CXCL13 (29% identical), CXCL6 (29% identical), CXCL2 (27% identical), PPBP (27% identical), CXCL8 (26% identical), PF4 (26% identical), PF4V1 (26% identical), CXCL1 (24% identical), CXCL5 (22% identical), CXCL3 (21% identical).
Diseases named in the same sentence as CXCL10 in open-access papers:
CXCL10 is named in the same sentence as 870 diseases in open-access papers, as found by Europe PMC text mining. Sharing a sentence is not in itself a finding about the gene and the disease. The quoted sentences say what the papers report.
COVID-19 (872 papers, 2020 to 2026). A disease caused by infection with severe acute respiratory syndrome coronavirus 2. "In COVID-19 patients, elevated CXCL10 levels are linked to disease severity and serve as a robust predictive biomarker for disease progression and mortality, while decreasing levels indicate clinical improvement." (PMID 39861921, 2025). "In the context of viral infections, elevated levels of CXCL9 and CXCL10 have been linked to hyperinflammatory states and disease severity, particularly in respiratory infections such as influenza and COVID-19." (PMID 41425601, 2025). "Recent studies on SARS-CoV-2 revealed that COVID-19-associated cytokine storms (CSs) show elevated levels of IL-1 beta, IL-6, CXCL10, TNF alpha, IFN gamma, MIP 1 alpha, and 1 beta, as well as MCP-1, GM-CSF, VEGF, and IL-10." (PMID 40358160, 2025). "Expression of Cxcl10, a biomarker associated with severe COVID-19 outcomes, was also significantly induced, with 20.4-fold and 6.2-fold increases at 3 and 6 dpi, respectively." (PMID 40822581, 2025). "CXCL10 levels in plasma and serum have been positively associated with the severity and progression of COVID-19 3–10." (PMID 39803542, 2024). "CXCL10 shows potential as a biomarker for predicting the duration of mechanical ventilation in patients with COVID-19-associated ARDS." (PMID 38745657, 2024). "In COVID-19, elevated levels of CXCL10 have been reported to be associated with a severe course and progression of the disease." (PMID 39415027, 2024). "As expression of many of the pro-inflammatory cytokines implicated in COVID-19 is NF-κB-dependent, including IL-6, TNFα, and CXCL10 among others." (PMID 39882243, 2024). "The underlying neuroinflammation in COVID-19 can be identified by detecting elevated levels of CXCL-10 in the CSF." (PMID 39205221, 2024). "CXCL-10 is associated with IL-6 secretion with raised levels seen in COVID-19 patients with pulmonary immune cell infiltration and cytokine storm." (PMID 39000027, 2024). "We also assessed the chemokine CXCL10 (C-X-C motif chemokine ligand 10), which has been identified as robust biomarker for COVID-19 outcome with elevated levels linked to acute respiratory stress syndrome (ARDS) and neurological complications." (PMID 39640591, 2024). "The increased presence of chemokines CCL2, CCL4, CXCL8, and CXCL10 in the plasma was observed among the Wuhan, Alpha, Delta, and Omicron variants of moderate to severe COVID-19 patients when compared to healthy individuals." (PMID 37632046, 2023). "Specifically, CCL2 and CXCL10 have been associated with an increased risk of death and poor prognosis in COVID-19 patients." (PMID 37497545, 2023). "We also found that TMPRSS2 and CXCL10 proteins are interconnected along with other protein components associated with COVID-19 development." (PMID 36239108, 2022). "Several studies reported positive correlations between CXCL10 and increased disease severity and risk of mortality in COVID-19 patients." (PMID 36341362, 2022). "In COVID-19 cases, levels of CXCL10 serum are highly associated with disease severity, viral load, and the Murray score." (PMID 35464491, 2022). "We also investigated the functional attitude of CXCL10 using the list of previously determined 1,656 commonly co-expressed genes which have association with prostate cancer and COVID-19 development." (PMID 36239108, 2022). "High levels of CXCL10 have been reported in severe cases of COVID-19 and associated with an increased detrimental inflammatory response." (PMID 36203752, 2022). "Some reports have shown that the CXCL10 concentration in serum is associated with poor prognosis in COVID-19+ patients." (PMID 35901034, 2022). "Elevated CXCL10 levels in BAL were associated with longer duration of mechanical ventilation in COVID-19 patients." (PMID 35371005, 2022). "Knowing that SARS-CoV-2 drives e.g., monocytes to induce host immune response, it seems that COVID-19 progression is associated with overexpression of CXCL10." (PMID 35409036, 2022).
COVID-19 (continued). "Recently, it was determined that CXCL10 is the most up-regulated chemokine associated with cytokine storm in COVID-19 infected patients." (PMID 36490282, 2022). "To date, elevated serum levels of CXCL-10 and IL-6 have been consistently reported in patients with COVID-19, as these are associated with an increased disease severity and risk of mortality." (PMID 35237279, 2022). "CXCL-10 has also been associated with a cytokine storm linked to more severe disease in COVID-19 patients." (PMID 35632654, 2022). "These were correlated with the extent of lymphopenia and CXCL10 associated with disease severity in COVID-19 patients." (PMID 35066575, 2022). "Based on our in silico analysis, it can be said that TMPRSS2 and CXCL10 can serve as biomarkers for analyzing the susceptibility of prostate cancer patients towards COVID-19." (PMID 36239108, 2022). "and chemokine (i.e., CXCL-10, IP-10) caused by COVID-19, and thus considerably alleviating the symptoms and the development of the COVID-19 in patients." (PMID 36506559, 2022). "Contrarily, elevated levels of CXCL10 were reported to be associated with COVID-19 severity and mortality." (PMID 35743825, 2022). "Altogether, these results indicate that the humoral response is inversely correlated with the level of plasma CXCL10, a biomarker associated with disease severity and age of COVID-19 patients." (PMID 36030261, 2022). "We observed increased expression of CCL13, CCL3, CXCL11 and CXCL10 which were associated with severe COVID-19 outcome in humans." (PMID 36298826, 2022). "Consistent with a protective role of N-specific T cells, these responses were also linked to reduced plasma concentrations of CXCL10 - a marker for COVID-19 disease severity." (PMID 36582222, 2022). "In this regard, it has been discussed that high production of some chemokines, such as CXCL8/IL-8, CCL-2/MCP-1, CCL3, CCL5, CXCL9, and CXCL10 are associated with lung damage and COVID-19 severity." (PMID 36685603, 2022). "The marked increase in CXCL10 and IL-6 corroborates previous studies describing the immune response in COVID-19 patients associated with disease severity and progression." (PMID 36451835, 2022). "In line with recent bioinformatic analysis of COVID-19 sequencing data we determined elevated expression of IFNγ -linked biomarkers, such as CXCL10, in both serum and nasopharyngeal swab material collected from patients with COVID-19." (PMID 35303909, 2022). "For identifying and analyzing co-expressed genes of ACE2 and CXCL10 associated with lung cancer and COVID-19 we constructed two Venn diagrams by listing the co-expressed genes of ACE2 and CXCL10 in each case of lung cancer and COVID-19." (PMID 33585826, 2021). "A total of 3544 commonly co-expressed genes associated with both lung cancer and COVID-19 were identified for ACE2 whereas the number of the commonly co-expressed genes of CXCL10 was 2088." (PMID 33585826, 2021). "Meanwhile, increased serum levels of IL-2, TNF-α, IL-7, granulocyte-colony stimulating factor and interferon-γ inducible protein 10 (CXCL10) are associated with COVID-19 disease severity." (PMID 33581688, 2021). "Bioinformatics analysis of GEO datasets for COVID-19 patients also identified CXCL-10 as the key cytokine linked to cytokine storm." (PMID 34745109, 2021). "On the other hand, to interpret the functional attitude of CXCL10 we used the list of 2088 commonly co-expressed genes of CXCL10 associated with lung cancer and COVID-19." (PMID 33585826, 2021). "We also found that ACE2 and CXCL10 proteins are interconnected along with other protein components associated with COVID-19 development." (PMID 33585826, 2021). "Recent reports claimed that C-X-C motif 10 (CXCL10), also known as Interferon gamma-induced protein 10 (IP-10) is one of the most crucial cytokines associated with COVID-19 disease severity." (PMID 33585826, 2021).
COVID-19 (continued). "After that, we looked forward to investigating the functional attitude of CXCL10 using the list of previously determined 2048 commonly co-expressed genes associated with lung cancer and COVID-19 development." (PMID 33585826, 2021). "Second, our team and others recently identified a unique cytokine response with higher concentrations of CXCL10 and GM-CSF in COVID-19 patients that were independently associated with outcomes." (PMID 34422854, 2021). "The two Venn diagrams revealed the commonly co-expressed genes of ACE2 and CXCL10 associated with lung cancer and COVID-19 development." (PMID 33585826, 2021). "By combining these two analyses, we can predict that overexpressed CXCL10 along with the presence of other cytokines causes cytokine storms in the alveoli of the COVID-19 infected lung cancer patients." (PMID 33585826, 2021). "Higher levels of several inflammatory cytokines including TNF-α, IL-6, and IL-1 and inflammatory chemokines such as CCL2, CCL3, and CXCL10 are associated with disease severity and death in COVID-19 patients." (PMID 33138195, 2020). "In this study, we identify a dysregulated cytokine production of GM-CSF and CXCL-10 in COVID-19 patients that was independently associated with the duration of MV which represents the distinctive poorer outcome observed in severe COVID-19 patients." (PMID 33272291, 2020). "This comprehensive evaluation of systemic and pulmonary immune response showed that the higher CXCL10 concentrations in both the systemic and alveolar compartments of patients with COVID-19 ARDS were associated with a longer duration of mechanical ventilation." (PMID 33138839, 2020). "Collectively, these results suggest that humoral immune responses are associated with the inflammatory factors IL-6, CXCL10, and C5a in COVID-19 patients." (PMID 32963357, 2020). "We identified a unique cytokine response, with higher plasma GM-CSF and CXCL10 in COVID-19 patients that were independently associated with the longer duration of mechanical ventilation." (PMID 33272291, 2020). "Recent reports highlight CXCL10 as a prognostic biomarker and critical pathogenic mediator of COVID-19." (PMID 33643285, 2020). "COVID-19 patients presented a unique phenotype associating higher levels of GM-CSF and CXCL10 and a longer duration of MV." (PMID 33272291, 2020). "Elevated innate immune cytokines detected in peripheral blood including interleukin (IL)-1, IL-6, IL-8, or C-X-C Motif Chemokine Ligand 10 (CXCL10) have been associated with severe or fatal COVID-19." (PMID 33010815, 2020). "CXCL10 has been proposed as a prognostic marker for the progression of disease in COVID-19, with continuously high levels of CXCL10 associated with worse outcomes." (PMID 33339864, 2020). "Notably, the Berb treatment reduced CXCL10 levels, which are associated with severe COVID-19 outcomes." (PMID 39640591, 2024). "However, under inflammatory conditions, such as colitis and Crohn’s disease, and infections, like COVID-19, the production of mainly CXCL10 strongly increases, which is associated with high tissue infiltration of activated CXCR3+ T cells." (PMID 39867906, 2024). "Additionally, the concentrations of CXCL1 and CXCL10 in the epithelial lining fluid (ELF) were also elevated in the COVID-19-associated ARDS." (PMID 38745657, 2024). "To determine the effect of Cxcl10 deficiency on histopathology, inflammation and virus load after MA10 SARS-CoV-2-infection, we harvested lung tissues on day 4 post infection, the day before the first death occurs in the model." (PMID 39803542, 2024). "CXCL10 had previously been associated with frailty in older population We found in our study that CXCL10 could be an interesting marker of COVID-19 severity and also seems to be associated with ageing." (PMID 38715114, 2024).